ALB (albumin)
Diseases named in the same sentence as ALB in open-access papers (continued):
Sharing a sentence is not in itself a finding about the gene and the disease.
COVID-19 (continued). "Of particular importance, higher age, male sex, ongoing intake of corticosteroids and lower serum albumin levels at presentation appear to be risk factors for severe COVID-19 in patients with glomerular diseases." (PMID 37767096, 2023). "A meta-analysis of 67 studies involving 19,760 COVID-19 patients emphasized that decreases in albumin levels were associated with both disease severity and worse outcomes in these patients." (PMID 36950410, 2023). "Mild pneumonia was also significantly associated with lower serum albumin level at the time of COVID-19 diagnosis (beta = – 6.317, 95% CI = – 9.448–− 3.185, P < 0.001)." (PMID 35877031, 2023). "We have previously demonstrated the prothrombotic role of serum albumin and D–dimer in patients with COVID-19 and that restoring serum albumin levels improves the thrombotic risk in this setting." (PMID 36650311, 2023). "Compared to discharged patients, patients with COVID-19 who died had higher nutritional and SP risk, lower albumin and total protein." (PMID 37234804, 2023). "Lower serum albumin levels at presentation were associated with severe COVID-19 outcomes in this cohort." (PMID 37767096, 2023). "Higher lymphocyte (B= -0.003, P=0.004) and Albumin (B= -0.252, P=0.036) had lower risk and better outcome of hospitality for COVID-19 patients, while IL-6 (B=0.004, P=0.045) increased the mortality and poor recovery risk, predict the unsatisfactory outcome." (PMID 38095633, 2023). "Risk factors for severe COVID-19 were older age, male sex, ongoing intake of corticosteroids and lower serum albumin levels at presentation." (PMID 37767096, 2023). "The results showed that OS levels measured at 10 min (>/=80%) were associated with poor survival in patients with COVID-19 and fully correlated with low albumin levels." (PMID 36982882, 2023). "Clinical data have shown that ALB levels are associated with the severity of COVID-19 patients, and patients with higher ALB levels (>35.8 g/L) show a better prognosis." (PMID 37511286, 2023). "Weight loss, decreased albumin level, and residual symptoms were observed in COVID-19-positive patients." (PMID 37501590, 2023). "Albumin, in particular, which is a marker of patients’ nutritional status, has been associated with COVID-19 severity." (PMID 36986138, 2023). "The reduced albumin-globulin ratio has been found to be a risk factor of COVID-19 severity in patients with cancer, and of great diagnostic significance in predicting the progression to severe disease states, which is consistent with our results." (PMID 37122321, 2023). "The multivariate analysis showed that older age, low albumin levels, and high globulin levels were significantly associated with severe COVID-19." (PMID 37823314, 2023). "Mild pneumonia was significantly associated with lower serum albumin level at the time of COVID-19 diagnosis (beta = – 6.317, 95% CI = – 9.448 to – 3.185, P < 0.001)." (PMID 35877031, 2023). "High Glucose, Urea, ALP and LDH levels and low Albumin and Potassium levels were associated with a more severe course of COVID-19." (PMID 37933044, 2023). "Currently, there have been studies indicating the association between ferritin/albumin and the prognosis of COVID-19 patients." (PMID 37817258, 2023). "Literature has also demonstrated that decreasing albumin levels are associated with poor outcomes and mortality in COVID-19 patients." (PMID 37841011, 2023). "Adjustments for albumin levels had the greatest impact on the association between circulating amino acids and COVID-19 severity; even associations with the most significant amino-acid levels were no longer significant, once adjusted for this covariate." (PMID 36837819, 2023). "Older age, male sex, ongoing intake of corticosteroids and lower serum albumin levels at presentation were identified as risk factors for severe COVID-19 outcomes in patients with a history of various immune-mediated glomerular diseases." (PMID 37767096, 2023).
COVID-19 (continued). "In this study, it was found that the increase of CRP, LDH levels and the drop of albumin level in the blood are laboratory parameters that were associated with increased COVID-19 severity." (PMID 37376524, 2023). "According to previous studies, lower serum albumin concentrations are associated with the disease severity and adverse outcomes in COVID-19 patients, as well as with poor prognosis." (PMID 36986138, 2023). "We found that COVID-19 severity was directly linked to age, scoring index of chest x-ray, percentage of neutrophils, albumin, CRP, and ratio of lymphocytes." (PMID 36668902, 2023). "The current study showed that the LDH/albumin ratio was an independent risk factor for in-hospital mortality in patients with severe ARDS due to COVID-19." (PMID 36197158, 2022). "Based on these studies, we examined BUN/albumin ratio in patients with severe ARDS caused by COVID-19." (PMID 36197158, 2022). "Elevated serum LDH levels and decreased serum albumin levels have been reported as risk factors for severe COVID-19." (PMID 36474652, 2022). "In COVID-19 patients, ALB was associated with amino acid metabolisms including serine, glycine, arginine, threonine metabolism, and proline histidine metabolism." (PMID 36091834, 2022). "Increased levels of neutrophil count, urea, AST, ALT, BILD, CK, LDH, D-dimer, CRP, PCT, Ferritin, reduced lymphocyte and monocyte count, decreased levels of albumin, and lower values of Sa02 and p02 are associated with the severity of COVID-19." (PMID 35075140, 2022). "LDH/albumin ratio can be used as an independent prognostic factor for mortality in patients with severe ARDS caused by COVID-19." (PMID 36197158, 2022). "Our study showed that features that were previously associated with COVID-19 severity in patients with cancer, such as low albumin, higher CRP, and neutrophils, remain discriminatory in patients who present with different variants." (PMID 36010932, 2022). "The most relevant observation of this retrospective analysis was that in a large sample of 1555 confirmed COVID-19 patients from hospitals of the community of Madrid, on-admission albumin levels predicted <30 days in-hospital all-cause mortality." (PMID 35160039, 2022). "Admission values of the De Ritis ratio, monocyte-to-lymphocyte ratio and D-dimer-to-albumin ratio exhibited association with in-hospital mortality in the general COVID-19 population." (PMID 36556433, 2022). "On the contrary, levels of A2MG and, especially ALB, decreased in association with COVID-19 severity." (PMID 36514048, 2022). "Several systematic reviews and meta-analyses have confirmed that older age, pre-existing CVD, higher troponin T concentration, higher C-reactive protein, and lower albumin are associated with increased mortality among patients hospitalized with COVID-19." (PMID 35837356, 2022). "Confirmed COVID-19 patients showing on-admission glucose levels above 125 mg/dL showed a significantly increased <30 days in-hospital all-cause mortality for all albumin levels, as compared with patients whose on-admission glucose levels were <125 mg/dL." (PMID 35160039, 2022). "Preschool-aged children with malnutrition usually suffer from anemia and low albumin levels that lower immunity, making them more susceptible to COVID-19." (PMID 35377892, 2022). "This meta-analysis of 10 observational studies on 3675 hospitalized patients diagnosed with COVID-19 showed a positive association of the fibrinogen-to-albumin ratio with poor prognostic outcomes." (PMID 35885582, 2022). "A meta-analysis of 67 studies had found that low albumin levels were associated with severity and worse prognosis in patients with COVID-19." (PMID 35601226, 2022). "Neutrophilia, high fibrinogen, low albumin and relatively normal triglyceride levels seen in COVID-19 associated cytokine storm (CS) and MIS-A; reveals the presence of a different clinical picture from other CSS." (PMID 35346086, 2022).
COVID-19 (continued). "Most undernourished preschool-aged children have low hemoglobin and albumin levels, which leads to a higher risk of infections, including COVID-19." (PMID 35377892, 2022). "Higher serum AST and ALT levels and lower serum albumin levels have been associated with COVID-19 severity." (PMID 35566563, 2022). "But one important observation we have come across is, progressive decline in albumin level, from admission to day 5, in COVID-19 infected cancer patients was significantly associated with death during the same hospital stay." (PMID 35350203, 2022). "Evidence in support of the association of fibrinogen and albumin with prognosis in patients with COVID-19 has prompted an exploration of the prognostic value of the F/A ratio in this clinical setting." (PMID 35885582, 2022). "It has been described in other articles that the clinical characteristics of patients with COVID-19 who have lower levels of serum albumin were related to a higher risk of death." (PMID 36558522, 2022). "In conclusion, the risk factors related to COVID-19 mortality in the Wenshan District of Taipei, Taiwan, were old age, comorbidities, and abnormal biomarkers such as low albumin level and elevated CPK and LDH levels." (PMID 35050031, 2022). "Albumin level, as an acute phase reactant, has been associated with both the adverse outcome of COVID-19 and the development of thrombotic events during COVID-19." (PMID 36028857, 2022). "The low level of albumin in preschool-aged children with undernutrition, which is below 3.5 g/dL (hypoalbuminemia), makes them more susceptible to COVID-19 because they have a lower ability to phagocytose and kill bacteria." (PMID 35377892, 2022). "The association between serum albumin concentrations and disease severity and mortality has been investigated also in COVID-19 patients." (PMID 35182287, 2022). "Due to the association between decreased serum albumin levels and higher disease severity, serum albumin can be used as a predictive biomarker for the severity of the disease in COVID-19 patients." (PMID 36267156, 2022). "Increased levels of WBC, neutrophils, CRP, ferritin, LDH, d-dimer, and IL-6, as well as decreased levels of lymphocytes, monocytes, and albumin have been associated with severe COVID-19 and worse outcomes." (PMID 35160073, 2022). "In the confirmed COVID-19 patients, the <30 days in-hospital all-cause mortality was inversely associated with on-admission albumin levels." (PMID 35160039, 2022). "In COVID-19 patients, as well as in other critical settings, low serum albumin is associated with poor outcomes, and albumin infusion has been suggested to be an effective treatment to improve prognosis in COVID-19." (PMID 34573989, 2021). "In line with previous evidence, we now report for the first time that combining IL-15 with albumin in a single prognostic ratio considerably improved our ability to identify COVID-19 patients at a much higher mortality risk." (PMID 34683480, 2021). "A recent meta-analysis has shown decreased serum albumin level has been associated with severe COVID-19 and mortality." (PMID 33853568, 2021). "First, decreased hepatic albumin production is associated with increased release of proinflammatory mediators belonging to the COVID-19-related cytokine storm, such as IL-6 and tumor necrosis factor-alpha (TNF-alpha)." (PMID 34683480, 2021). "Serum albumin is decreased in severe cases although a significant impairment of liver function as the cause of death in COVID-19 rarely occurs." (PMID 33777864, 2021). "Several clinical markers predictive of SARS-CoV-2 positivity in this study have previously been associated with severe COVID-19, including decreased white blood cell count, platelet count, serum albumin levels, respiratory rate, and diastolic blood pressure." (PMID 34648552, 2021).
COVID-19 (continued). "The COVID-19 patients also had signs of protein loss such as reduced levels of albumin and impaired organ function, highlighting the role of nutrition risk screening and its prognostic value for COVID-19 patients." (PMID 34034769, 2021). "In summary, combining urinary SARS-CoV-2 N and plasma albumin levels at ICU admission allowed for a more robust identification of patients at risk for AKI in COVID-19 as compared to analysis of the single markers alone." (PMID 34113632, 2021). "The results of 10 data training showed that percentage of neutrophils, saturation of pulse oxygen at admission, alanine aminotransferase, sex, and albumin were possibly associated with the survival of COVID-19 patients." (PMID 34631727, 2021). "The Controlling Nutritional Status (CONUT), an index calculated on the base of lymphocyte count, total cholesterol, and serum albumin, was found to be a further risk factor for the death of COVID-19 patients." (PMID 33801645, 2021). "These biomarkers for susceptibility to severe COVID-19 include lower levels of omega-3 omega-6 fatty acids as well as albumin, and higher levels of GlycA." (PMID 33942721, 2021). "Low-serum albumin levels in studies with COVID-19 patients are suggested to be associated with an increased risk of mortality." (PMID 34284639, 2021). "Meanwhile, those in the highest tertile for albumin had a decreased risk of COVID-19 death (HR: 0.12, 95% CI: 0.03–0.51)." (PMID 34400804, 2021). "To further analyze these parameters as hypothetic drivers of COVID-19, we plotted the earliest available and lowest serum albumin and AT-III levels of the three risk groups." (PMID 34300217, 2021). "The reference range of HSA concentration in serum is approximately 35–50 mg/ml, but we and other groups found that COVID-19 associated mortality correlates with lowered [albumin] <30 mg/ml." (PMID 34821549, 2021). "In this sense, we show that combining laboratory markers’ values with serum cytokines is an excellent strategy to improve the early recognition of COVID-19 patients with an increased risk of death, mainly albumin and IL-15." (PMID 34683480, 2021). "Eight clinical markers of lactate dehydrogenase, C-reactive protein, albumin, comorbidity, electrolyte disturbance, coagulation function, eosinophil and lymphocyte counts were associated with the severity of COVID-19." (PMID 34372792, 2021). "The aim of this present study was to appraise the available evidence regarding the associations between serum albumin concentrations, disease severity and adverse outcomes in COVID-19 patients." (PMID 33511503, 2021). "The low albumin has been associated with adverse outcomes in various other disease conditions, as well as in COVID-19 patients who were hospitalized." (PMID 33930096, 2021). "The combined use of laboratory parameters with inflammatory markers increases the ability to identify COVID-19 patients at a higher mortality risk, as with serum albumin, C-reactive protein (CRP), and neutrophilia." (PMID 34683480, 2021). "CRP and albumin, which are acute phase reactants, are associated with severe COVID-19, a highly inflammatory state." (PMID 34123422, 2021). "The peak levels of NAbs were positively associated with severity of COVID-19 and age, while negatively associated with serum albumin levels." (PMID 34006847, 2021). "Lab markers such as raised TLC, ferritin, D-dimer, and low albumin were associated with worse outcomes in our subset of COVID-19-related illness." (PMID 34646702, 2021). "Several risk factors contributing to the progression of COVID-19 were identified, including age, maximum body temperature at admission, respiratory failure, albumin level, and C-reactive protein (CRP)." (PMID 34673806, 2021). "For this reason, we suggest the use of the IL-15-to-albumin ratio with cut-off point >105.4 to triage COVID-19 patients with increased mortality risk, which becomes more relevant in countries with slow vaccination rates." (PMID 34683480, 2021).
COVID-19 (continued). "In our study, COVID-19 mortality was associated with four biomarkers: serum albumin, direct bilirubin, total leucocyte count, and respiratory rate." (PMID 34055545, 2021). "Growing evidence has shown that COVID-19 is associated with a strong cytokine storm and, consequently, the consumption of albumin." (PMID 34337084, 2021). "A recent study showed that reduced serum albumin levels were associated with increased mortality in COVID-19 patients." (PMID 33445583, 2021). "Our findings provided an important piece of evidence that both elevated CRP and decreased albumin were independently associated with hospital long-stay in patients with moderate COVID-19." (PMID 33853568, 2021). "Indicators that represented organ damages, such as elevated ALT, AST, LDH, creatinine, amylase, hs-cTnI, NT-proBNP, CK-MB, and decreased ALB/GLO aggrandized the risk for COVID-19 death." (PMID 34521370, 2021). "Our study showed an inverse relationship between the level of albumin and the risk of death in COVID-19 patients." (PMID 33759606, 2021). "It was also confirmed in our study that saturation of pulse oxygen at admission and albumin were associated with the survival of COVID-19 patients." (PMID 34631727, 2021). "Oxidation of –SH groups of albumin is known to occur in pathophysiological processes associated with increased inflammation and oxidative stress and potentially in COVID-19 patients." (PMID 33562403, 2021). "In the current study, we found an independent association between serum free thiol concentrations and albumin concentrations in both COVID-19 subjects and healthy controls." (PMID 34943125, 2021). "Age and duration of COVID-19 were also positively associated with peak NAbs, while serum albumin level was negatively associated with peak NAbs." (PMID 34006847, 2021). "In the light of these established functions, it is natural to suggest albumin as a frontline protection against COVID-19-associated lethality resulting from cytokine storm, oxidative stress, blood clotting, and the ensuing organ failure." (PMID 34821549, 2021). "Low serum albumin induces fluid overload, pulmonary edema and circulatory failure, all of which are known to be major causes of death in COVID-19 multiorgan involvement." (PMID 34300217, 2021). "In conclusion, COVID-19 patients with higher albumin levels on admission were associated with a better overall prognosis." (PMID 33725003, 2021). "Higher AST, ALT, GGT and lower ALP, albumin and PT were associated with severe clinical presentation of COVID-19 (p < 0.05 for all analyses)." (PMID 34575333, 2021). "Decreased albumin levels were very highly associated with COVID-19 mortality in our data set, having the largest effect size for any laboratory measurement in the univariable analysis (HR2SD = 0.471 [0.442;0.503], P = 5.10E-110)." (PMID 35602191, 2021). "Although the field of COVID-19 research is rapidly growing, few studies have examined the association between albumin levels and COVID-19 disease severity." (PMID 33725003, 2021). "Based on multivariate analyses, decreased apoA-1 and HDL-C levels were independently associated with COVID-19 severity after adjusting for established indicators of severity, such as age, low albumin, and increased D-dimer, CRP, and IL-6 levels." (PMID 33344516, 2020). "For the same therapeutic purpose, the MNBC expressed a predisposition to ensure the supply for the COVID-19 infected patients in case of need for stable blood products such immune-globulins and albumin." (PMID 33598089, 2020). "Adecrease in the levels of albumin is most likely due to liver damage and is likelyto be caused by adverse drug reactions and systemic inflammation in critically illpatients with COVID-19." (PMID 32490680, 2020). "Contemporaneous increase in ferritin, IL-6 and ALT levels associated with decreased albumin concentration suggest more significant liver involvement in the course of COVID-19." (PMID 32403255, 2020).